IL17F (interleukin 17F)
Diseases named in the same sentence as IL17F in open-access papers (continued):
Sharing a sentence is not in itself a finding about the gene and the disease.
cancer (31 papers, 2012 to 2025). A tumor composed of atypical neoplastic, often pleomorphic cells that invade other tissues. "The correlation between IL-17F polymorphism and cancer incidence or patients’ prognosis seemed to be weak in every cancer analyzed." (PMID 35012470, 2022). "We applied systematic review guidelines to study the role of IL-17F, protein and mRNA expression, polymorphisms, and functions, in cancer." (PMID 35012470, 2022). "Other IL-17F SNPs has been less extensively analyzed, and more studies are needed to confirm the relevance of IL-17F polymorphisms in various cancers." (PMID 35012470, 2022). "In 2014, two researchers independently performed a meta-analysis and attempted to elucidate the relationship between IL-17A rs2275913 and IL-17F rs763780 and cancer risk in Asians." (PMID 36300118, 2022). "Here, we systematically collected literature concerning the expression, polymorphisms, and function of IL-17F in various cancers and reviewed the role of IL-17F as a pro- or antitumorigenic molecule." (PMID 35012470, 2022). "The association between IL-17F polymorphisms and cancer was another important aspect in this review, but again the results were variable." (PMID 35012470, 2022). "In this systematic review, we aimed to clarify the role of IL-17F, protein and mRNA expression and polymorphisms, in cancer and the mechanisms through which IL-17F affects cancer development and progression." (PMID 35012470, 2022). "The aim of the present work was to clarify the effects of IL-17A G197A (rs2275913) and IL-17F T7488C (rs763780) polymorphisms on cancer risk." (PMID 26843459, 2016). "Our study represents a comprehensive meta-analysis of the role of IL-17A rs2275913 and IL-17F rs763780 polymorphisms in cancer risk." (PMID 26843459, 2016). "Many epidemiological studies have focused on the association of the IL-17A rs2275913G>A and IL-17F rs763780T>C polymorphisms with cancer risk." (PMID 25147431, 2014). "Odds ratios (ORs) with 95% confidence intervals (CIs) were used to assess the association of the IL-17A rs2275913G>A and IL-17F rs763780T>C polymorphisms with cancer risk." (PMID 25147431, 2014). "The IL-17F rs763780 polymorphism was identified as a missense mutation located in the coding region, with the amino acid modification of the conversion of His to Arg, resulting in potential changes in protein expression and possible cancer risk." (PMID 35410225, 2022). "Eight IL-17F SNPs (rs763780, rs9382084, rs12203582, rs1266828, rs2397084, rs7771511, rs641701, and rs9463772) were studied in terms of their association with 13 types of cancer in 38 studies." (PMID 35012470, 2022). "Therefore, we performed a meta-analysis to clarify the possible association of the IL-17A rs2275913G>A and IL-17F rs763780T>C polymorphisms with cancer risk." (PMID 25147431, 2014). "Another closely related cytokine, IL-17F, reportedly exerts protective effects against various cancer types, including HNSCC and pancreatic cancer." (PMID 40974979, 2025). "Previously, we demonstrated that, in OTSCC, IL-17F has antitumorigenic effects by inhibiting cancer cell proliferation, migration, and angiogenesis." (PMID 40974979, 2025). "Unclear, elevated levels of IL-17RC in CRPC; higher expression of IL-17F in cancers with higher histological grades." (PMID 37371647, 2023). "In contrast to IL-17A, which has already been studied intensively, IL-17F has thus far received much less attention in the cancer research field." (PMID 35012470, 2022). "This variation in the role of IL-17F in different cancers is common also in other proteins such as MMP-8." (PMID 35012470, 2022). "Nevertheless, this review gives an overall picture of the variable IL-17F roles in different cancers." (PMID 35012470, 2022). "We also analysed data related to the proposed molecular mechanisms by which IL-17F affects cancer development and progression." (PMID 35012470, 2022).
cancer (continued). "The correlation between IL-17F expression and cancer has been studied in 13 different cancers in 34 publications." (PMID 35012470, 2022). "Other antitumorigenic mechanisms of IL-17F included the inhibition of cancer cell proliferation and migration and cell cycle regulation." (PMID 35012470, 2022). "The findings indicated that IL-17F has both anti- and protumorigenic roles, which depend on cancer type and the molecular form and location of IL-17F." (PMID 35012470, 2022). "Fusobacterium nucleatum, which has been linked to chronic inflammation and cancer, aggravates intestinal inflammation in mice by targeting caspase activation and recruitment domain 3 through NOD2, eventually activating the IL-17F/NF-κB pathway." (PMID 33244315, 2020). "As for IL-17A, the role of IL-17B, IL-17C, IL-17D, IL-17E, and IL-17F in cancer remain controversial." (PMID 33244315, 2020). "Since an opposite effect has been reported for IL-17A (which shares the highest homology with IL-17F) on cancer cells, we also investigated the influence of this cytokine on OTSCC cell proliferation." (PMID 31083515, 2019). "IL-17F effects on cancer cell proliferation, migration, and invasion were studied using a live-imaging IncuCyte system, and a Caspase-3/7 reagent was used for testing apoptosis." (PMID 31083515, 2019). "Th17 cells are generally important mediators of inflammation, autoimmune diseases and cancer, particularly through the production of IL-17A and IL-17F." (PMID 22461912, 2012). "The IL-17 family of cytokines is composed of six members named IL-17A (commonly known as IL-17), IL-17B, IL-17C, IL-17D, IL-17E (also known as IL-25), and IL-17F with different sequence homology and functions that are important players in host defense responses, inflammation, and cancer development." (PMID 38068860, 2023). "Based on the collected data, IL-17F seems to play a role in cancer development and progression." (PMID 35012470, 2022). "Effects of IL-17F on cancer progression were shown to be through several different mechanisms." (PMID 35012470, 2022). "Other members, including IL-17F, have been far less extensively studied, also in cancer." (PMID 35012470, 2022). "Although Th17-associated cytokine genes (IL17A and IL17F) were not affected, we still observed that Th17 cells showed significantly decreased abundance at the late stage of cancer progression, which is inconsistent with previous findings." (PMID 36352434, 2022). "IL-17A, IL-17B, IL-17C, as well as IL-17F have been shown to promote tumor development, whereas IL-17D and IL-17E play anti-cancer roles in a context-dependent manner by activating the Nrf2 stress surveillance pathway, recruiting innate immune cells, and activating leukocytes." (PMID 36140808, 2022). "No solid evidence emerged for the correlation between IL-17F polymorphisms and cancer incidence or patients’ prognosis." (PMID 35012470, 2022). "For example, a dysregulated IL-17A and IL-17F production can impair myeloid cell recruitment and determine an excessive pro-inflammatory cytokine expression, and consequently chronic inflammation, which leads to cancer development." (PMID 36432658, 2022). "We therefore studied the effects of IL-17F on cancer cell migration in vitro." (PMID 31083515, 2019). "Beyond its influence on cancer cells, IL-17F significantly suppressed HUVEC tube formation." (PMID 31083515, 2019). "To determine whether IL-17F influences cancer cell proliferation, we conducted a label-free proliferation assay on HSC-3 and SCC-25 cells." (PMID 31083515, 2019). "Therefore, Th17 cells and IL-17F have been suggested as promising therapeutic tools in cancer patients." (PMID 31083515, 2019). "IL-17F, the newest member of the IL-17 family that shares the greatest homology with IL-17A, was reported to provide protective effects against several types of cancer, such as oral, colon, and hepatocellular carcinoma." (PMID 31083515, 2019).
cancer (continued). "The proinflammatory cytokines IL-17A and IL-17F can mediate inflammation and cancer." (PMID 22461912, 2012). "Cancer histology grouped into gastrointestinal (GI), genitourinary (GU), upper aerodigestive (UAD), skin, and other showed differences in plasma levels of IL-8, IL-17f, IP-10, and RANTES at baseline (P < 0.05)." (PMID 39403935, 2024). "In our previous study, we reported that cancer cells exhibited negative immunoreactivity to IL-17F in >75% of OTSCC patients." (PMID 31083515, 2019). "While IL-17A plays important roles in cancer development, the function of IL-17F in tumorigenesis has not yet been elucidated." (PMID 22509371, 2012). "Furthermore, we showed in our recent multicenter study that MC-derived extracellular (rather than intracellular) IL-17F at the cancer invasion front correlates with better disease-specific survival in OTSCC patients." (PMID 31083515, 2019). "While it is difficult to arrive at a solid conclusion on the mechanism behind this effect based on our results, we suggest that IL-17F may interfere with the CAF–cancer cell interaction, since we did not see a decrease of invasion on the cancer cells alone." (PMID 31083515, 2019).
bacterial infection (9 papers, 2011 to 2025). "Reports indicate that both IL‐17F and IL‐17A are required for protection against bacterial infection." (PMID 38660962, 2024). "Although mammalian IL-17A and IL-17F have many overlapping functions, they play different roles in host defense against bacterial infection." (PMID 34267744, 2021). "Given the observations of increased IL-17 expression in CTCL patients with bacterial infections, we propose a link between bacterial infection, expression of IL-17F and the disease progression." (PMID 23949004, 2013). "IL-17A and IL-17F are produced by Th17 cells and play major roles in neutrophil recruitment and protection against intracellular and extracellular bacterial infections." (PMID 21738762, 2011). "Specifically, SOR pre-inoculation upregulated the expression of the IL17F gene and robustly activated pathways related to bacterial infection, lgA production, virus protein interaction with cytokine, complement response, and IL-17 signaling pathways during influenza virus infection." (PMID 40858544, 2025). "IL‐17A and IL‐17F play important roles in host defense against bacterial infections." (PMID 38660962, 2024). "IL-17A and IL-17F are able to induce proinflammatory cytokines, chemokines and antimicrobial peptide expression, as well as to promote neutrophil recruitment and provide mucosal host defenses against fungal and bacterial infections." (PMID 22675469, 2012).
inflammation (6 papers, 2011 to 2025). Aberrant reaction of the microcirculation characterized by movement of fluid and leukocytes from the blood into extravascular tissues. "Some studies show a variety of IL-17F roles in the pathogenesis of airway inflammation due to an allergic reaction." (PMID 28606156, 2017). "Some studies has shown variety of IL-17F roles in the pathogenesis of airway inflammation due to an allergic reaction." (PMID 28606156, 2017). "In addition, IL-17A and IL-17F stimulate keratinocytes and activate vascular inflammation." (PMID 32380665, 2020). "Consistent with liver inflammation, the serum levels of pro-inflammatory proteins, including CCL2, CXCL9, IL-17a, IL-17f, and TNF receptor superfamily member 12a, were increased in HF-HC-fed mice." (PMID 41362710, 2025).
neurodegenerative disease (2 papers, 2015 to 2024). A disorder of the central nervous system characterized by gradual and progressive loss of neural tissue and neurologic function. "IL-17RC serves as an essential subunit of the IL-17 receptor complex and mediates the signal transduction and proinflammatory activities of IL-17A and IL-17F, which have been implicated in autoimmune and neurodegenerative diseases." (PMID 26504591, 2015). "IL-17F induces expression of pro-inflammatory mediators in ALS and other neurodegenerative diseases, and elevated IL-17 levels are found in ALS patients." (PMID 38612591, 2024).
infectious disease (1 paper, 2020). A disorder directly resulting from the presence and activity of a microbial, viral, or parasitic agent in humans. "Although in humans IL-17F and IL-17A are encoded by genes that are located in the same chromosomal region (6p12) there is evidence for differences in gene regulation and expression of both isoforms in the context of infectious diseases." (PMID 33322218, 2020).
intestinal disease (1 paper, 2018). "Inhibition of IL17A and IL17F in the absence of IFNγ partially protected mice from developing intestinal disease." (PMID 29416538, 2018).
kidney (1 paper, 2020). "The transcription levels of IL-17F (a subfamily of IL-17), IL-23 (an inducing factor of IL-17A), and Foxp3 (a marker for regulatory T cells) were altered in the kidneys of both adenine-induced kidney injury groups; the levels were comparable between SPF and GF groups." (PMID 32859011, 2020).
neurological disorders (1 paper, 2024). "IL-17 is a pro-inflammatory cytokine mainly produced by γδ T cells and Th 17 cells, including six members (IL-17A to IL-17F), which have an important role in neurological disorders." (PMID 38783945, 2024).
vasculopathy (1 paper, 2023). "Notwithstanding, IL-17A, IL-17F, and IL-17E were demonstrated to promote vasculopathy in SSc patients." (PMID 37239000, 2023).
IL17F also shares sentences with these, for which no sentence is quoted: dermatitis (8 papers); chronic periodontitis (7); autoimmune polyendocrine syndrome type 1 (3); Primary Sjögren's Syndrome (3); pulmonary fibrosis (3); thyroid cancer (3); acute myocardial infarction (2); adenocarcinoma (2); allergies (2); aseptic meningitis (2); hepatitis C (2); Hyperkeratosis (2); idiopathic pulmonary fibrosis (2); immune diseases (2); intestinal inflammation (2); malaria (2); rectal cancer (2); schistosomiasis (2); acute laryngitis (1); AIDS (1); alcoholic fatty liver disease (1); Alzheimer disease (1); Amoebiasis (1); anaplastic large cell lymphoma (1); anterior uveitis (1); ataxia telangiectasia (1); autoimmune Addison's disease (1); autoimmune gastritis (1); autoimmune polyendocrinopathy (1); Autosomal dominant hyper-IgE syndrome (1).
A further 62 diseases each share a sentence with IL17F in 1 paper.